MDM2 (MDM2 proto-oncogene)
Diseases named in the same sentence as MDM2 in open-access papers (continued):
Sharing a sentence is not in itself a finding about the gene and the disease.
breast carcinoma (continued). "A specific polymorphism in MDM2 (SNP309) markedly increases the risk of developing breast cancer." (PMID 40191734, 2025). "Our study provides evidence that MDM2 promoter polymorphisms may be associated with neutrophil counts and bone marrow recovery during chemotherapy treatment in breast cancer patients." (PMID 39979836, 2025). "MDM2 has been demonstrated to be closely associated with breast cancer invasion and metastasis." (PMID 37818185, 2023). "MDM2 is proved to be associated with chemoresistance in many tumors, including breast cancer." (PMID 37217945, 2023). "14-3-3 sigma and MDM2 are associated with the oncogenesis in breast cancer." (PMID 35890172, 2022). "We hypothesized that MDM2 inhibition may represent an alternative therapeutic strategy in endocrine therapy-resistant breast cancers harboring GATA3 mutations." (PMID 35440675, 2022). "In addition, as FKBP1A degrades MDM2, it makes cells susceptible to chemotherapy-induced apoptosis; in breast cancer patients with high MDM2 expression, FKBP1A elevated sensitivity to anthracycline chemotherapeutic agents." (PMID 36499275, 2022). "Recently, in other types of cancer, the variant genotypes of MDM2 rs2279744 and/or rs3730485 were reported as risk factors for breast cancer but with a trend towards a good prognosis, for laryngeal, gynecological cancers, and in haplotype analysis for papillary thyroid carcinoma." (PMID 32492903, 2020). "MDM2 SNP309 was found associated with the onset age of breast cancer in several studies." (PMID 33202864, 2020). "Increased MDM2 expression in breast cancer tissue is associated with poor prognosis." (PMID 30642351, 2019). "Consistently, we found an association of the age at breast cancer onset with MDM2 mRNA expression." (PMID 30691044, 2019). "In addition, increased expression of MDM2 is associated with many tumor types including melanoma, colon and breast cancers." (PMID 28418896, 2017). "Thus, we believe that triptolide should be a promising new MDM2 inhibitor and particularly efficient for the treatment of high-risk, refractory breast cancer patients." (PMID 27004407, 2016). "While evidence linking SNP34091 status to breast cancer risk has been at variance, we recently found the MDM4 SNP34091AC genotype to be associated with a reduced risk of breast cancer among individuals carrying the MDM2 SNP309GG genotype, a genotype, in general, associated with elevated cancer risk." (PMID 26867771, 2016). "Therefore, the present study was aimed to find out the possible association between 40-bp ins/del polymorphism in the promoter region of MDM2 and breast cancer in a sample of Iranian population." (PMID 25326024, 2014). "Higher expression of MDM2 increases the lifetime risk of developing breast cancer." (PMID 25326024, 2014).
breast carcinoma (continued). "Except for MLH1-rs1799977 and MDM2-rs769412, this model captured distinct set of SNPs from the ones profiled in the two-way epistatic interactions, suggesting a possible convergence of multiple DNA repair pathways while conferring breast cancer risk." (PMID 23755158, 2014). "Reports suggest that MDM2 T309G variation could increase risk of sarcoma, endometrial, hepatocellular and breast cancers." (PMID 22844496, 2012). "Thus different results as to the effect of MDM2 309 SNP on breast cancer onset age in BRCA1/2 mutation carriers and in the non carrier control Ashkenazi group were obtained by different groups." (PMID 19226467, 2009). "Similar to the risk estimation, whether MDM2 SNP309 is associated with an earlier age onset of breast cancer remains controversial." (PMID 19144119, 2009). "Together, these data indicate that the homozygous MDM2 SNP309 GG genotype may increase the risk of breast cancer in Taiwanese women." (PMID 19144119, 2009). "Interestingly, a recent report showed that in the Chinese population, MDM2 SNP309 G allele increased the risk of sporadic breast cancer, but the T allele was associated with earlier onset." (PMID 19144119, 2009). "Given that the main immigrants of Taiwan are from mainland China, this implies that the effects of MDM2 SNP309 on the risk of breast cancer may be associated with environmental discrepancy and confined to the selected subgroups even in similar ethnicities." (PMID 19144119, 2009). "Findings based on the current sample size suggest that the MDM2 SNP309 GG genotype may be associated with both the risk of breast cancer and an earlier age of onset in Taiwanese women." (PMID 19144119, 2009). "Also, aberrant alternative splicing of MDM2 transcripts were found to associate with a prognostic factor for poor survival in patients with breast cancer, whereas HDMX has been linked to soft-tissue sarcoma." (PMID 19516963, 2008). "Similarly, the MDM2 rs937282 polymorphism has been linked to lung cancer and breast cancer, while MDM2 rs937283 has been implicated in retinoblastoma, oral cancer, thyroid cancer, breast cancer, gastric cancer, and liver cancer." (PMID 39857959, 2025). "The expression of Livin and MDM2 in paired breast cancer tissues pre- and post-NAC was examined by IHC." (PMID 41551910, 2026). "These two PROTACs directly penetrate breast cancer cells and effectively recruit the E3 ligase mouse double minute 2 homolog (MDM2) to SETDB1, inducing proteasome-dependent degradation of SETDB1." (PMID 41498743, 2026). "Based on these results, we suggest, 3’UTR editing to be a contributor to increased MDM2 expression in breast cancers and propose that MDM2 protein can be significantly downregulated by ADAR1 inhibition." (PMID 40381037, 2025). "It suppresses apoptosis in lapatinib-resistant HER2+ breast cancer, indicating a potential role for MDM2 inhibition in overcoming lapatinib resistance." (PMID 40949156, 2025).
breast carcinoma (continued). "The overexpression and amplification of the MDM2 oncogene frequently occur in breast cancer, correlating with high tumor grade and serving as an independent negative prognostic marker in human breast cancer." (PMID 40046748, 2025). "The study enrolled patients with MDM2-amplified solid tumors, including, for example, sarcoma, breast cancer, and cholangiocarcinoma." (PMID 41299419, 2025). "This investigation utilized a comprehensive computational strategy to assess the anti-breast cancer potential targeting the MDM2 protein among 398 terpenoids sourced from the NPACT database." (PMID 40308267, 2025). "We found the MDM2 polymorphisms SNP309 and del1518 to be associated with neutrophil recovery during neoadjuvant chemotherapy in breast cancer patients." (PMID 39979836, 2025). "A reporter assay for MDM2, an oncogene overexpressed mostly in luminal breast cancers, demonstrated that RNA editing enhances protein expression, in agreement with reduced MDM2 protein levels in ADAR1 knockdown cells." (PMID 40381037, 2025). "Dysregulation of the subcellular localization of MDM2 is another critical factor that promotes enhanced MDM2 activity in human breast cancer cells." (PMID 40191734, 2025). "In patients with breast cancer in the advanced stages of metastasis, SMAD family member 3 (SMAD3) has been implicated in inducing MDM2 transcription via its second promoter." (PMID 40191734, 2025). "Their improved binding efficiency, reduced reactivity, and enhanced pharmacokinetic profiles advance current research on MDM2 inhibition, offering promising candidates for breast cancer therapy." (PMID 40308267, 2025). "Using TCGA RNA-seq data, we identified differentially edited 3’UTRs in breast cancers and experimentally validated editing sites in the 3’UTRs of MDM2, GINS1, and F11R regulated by ADAR1 with protein level implications." (PMID 40381037, 2025). "Alizarin represented a promising approach to inhibit cell proliferation of breast cancer by modulating estrogen receptor mediated effects on MDM2/p-Rb/E2F1 axis concomitantly with activating apoptosis of cancer cells." (PMID 40580306, 2025). "In closing this study highlights the significance of A-to-I(G) RNA editing in the 3’UTR of MDM2 and its contribution to increased MDM2 expression in breast cancers." (PMID 40381037, 2025). "In HER2- and MDM2-enriched breast cancer subtypes, NBN plays a role in doxorubicin, paclitaxel, and carboplatin resistance via its involvement in DNA repair and homologous recombination." (PMID 41375077, 2025).
breast carcinoma (continued). "Studies have also revealed that inhibiting MDM2 expression reduces DNA repair mediated by homologous recombination and sensitizes breast cancer cells to PARPi olaparib." (PMID 40949156, 2025). "Curiously, MDM2 is most significantly overexpressed in luminal A (lumA) breast cancers in the TCGA dataset compared with normal breast tissue or adjacent normal tissue." (PMID 40381037, 2025). "Our findings contribute to current breast cancer research by identifying novel, pharmacologically viable natural terpenoid inhibitors that target MDM2 with greater stability and selectivity than previously studied compounds." (PMID 40308267, 2025). "An additional clinical trial (NCT03566485) investigated the activity of the MDM2 iidasanutlin, an MDM2 antagonist in breast cancer cells." (PMID 40191734, 2025). "Studies suggest MDM2 is overexpressed in breast cancer cells positive for estrogen receptor 1 (ESR1/ER-alpha)." (PMID 40191734, 2025). "A study of Caucasian women found that MDM2 with a mutant C allele for the SNP285 polymorphism was less susceptible to overexpression and protected against breast cancer." (PMID 40191734, 2025). "It included three patients with breast cancer, of whom one showed stable disease with an approximately 20% increase in tumor size, one showed a reduction in tumor size but elevated MDM2 levels, and one showed a progressive tumor increase of >20%." (PMID 40191734, 2025). "Genotyping blood DNA from 108 breast cancer patients, we found the minor allele frequencies (MAF) for MDM2 SNP309 (rs2279744), SNP285 (rs117039649) and del1518 (rs3730485) to be 0.36, 0.05 and 0.37, respectively." (PMID 39979836, 2025). "In breast cancer, MDM2 overexpression occurs in approximately 6% of cases, with this increasing to 14% in the TNBC subtype." (PMID 39940844, 2025). "Oncoprotein MDM2 is also highly expressed in many human cancers, including colorectal adenocarcinoma, breast carcinoma, and lung cancer." (PMID 37867415, 2024). "Future studies will be needed to determine the best practice and compounds for the simultaneous inhibition of the CXCL12/CXCR4 axis and the MDM2/MDMX axis to block breast cancer metastasis." (PMID 39766093, 2024).
breast carcinoma (continued). "The expression of MDM2 is positively correlated with ERα expression in human breast cancer tissues and cell lines." (PMID 38741108, 2024). "High expression of MDM4 and MDM2 occurs frequently in human cancers, including breast cancer, gliomas, soft tissue sarcomas, and melanomas." (PMID 39345743, 2024). "As a multifunctional oncoprotein, murine double minute 2 (MDM2) is found to be overexpressed in patients with a variety of cancers, including breast cancer." (PMID 37217945, 2023). "A novel inhibitor of MDM2 (termed SP-141) exerts anti-breast cancer activity in vitro and in vivo via directly binding to MDM2 and promoting MDM2 proteasomal degradation." (PMID 37291112, 2023). "Screening and reviewing the literature regarding MDM2 amplification, we noticed that several studies used assessment criteria similar to the ones reported in breast cancer HER2 evaluation guidelines." (PMID 36674856, 2023). "Another PROTAC tractable target is Rac Family Small GTPase 1 (RAC1), inducing chemoresistance of breast cancer, interacts with co-opted E3 ligases MDM2 and XIAP, and potentially novel E3 ligases, ITCH and SMURF2." (PMID 37845222, 2023). "In a study, silencing the expression of MDM2 in breast cancer led to decreased vascularization in primary tumor tissue along with a significantly lower number of circulating cells." (PMID 37314603, 2023). "STEMVAC is a multi-Ag plasmid DNA vaccine encoding Th1 epitopes of CD105, Yb-1, SOX2, CDH3, and MDM2: five important TAAs associated with cancer stem cells and the EMT process in breast cancer." (PMID 36679991, 2023). "In-vivo study on breast cancer demonstrated that the cells transfected with MDM2 showed high resistance to doxorubicin." (PMID 37314603, 2023). "The authors also showed that in a subset of breast cancer mutants, MDM2 activates the E2F1 pathway via phosphorylation of Rb." (PMID 37314603, 2023). "In breast cancer cells, elevated MDM2 levels were correlated with resistance against TGF-β1 treatment." (PMID 37314603, 2023). "The observations of aberrant regulation of GR in neuroblastoma, ER in breast cancer, and AR in prostate cancer along with the elevated level of MDM2 in advanced stages evinced the strong correlation of MDM2 with steroid regulation." (PMID 37314603, 2023). "Further evidence from studies on breast cancer suggests that MDM2 promotes cell motility and invasiveness of breast cancer cells by targeting E-cadherin for degradation and inducing MMP9 expression." (PMID 37138218, 2023). "By disrupting the MDM2–HAUSP–DAXX-HAUSP-DAXX complex, S100A6 induces MDM2 self-ubiquitination and its degradation, which suppresses the growth of breast cancer and enhances its sensitivity to chemotherapy." (PMID 37217945, 2023).